BMI1 (BMI1 proto-oncogene, polycomb ring finger)
Diseases named in the same sentence as BMI1 in open-access papers (continued):
Sharing a sentence is not in itself a finding about the gene and the disease.
cancer (continued). "In HNSCC, Cisplatin-resistant cancer cells display a distinct increase in expression of Bmi-1 among other stemness markers, as opposed to Cisplatin-sensitive cancer cells." (PMID 34689150, 2021). "In this study, we found that pharmacological inhibition and knockdown of BMI-1 increases apoptosis in cancer cells, but not in normal cells, and induces downregulation of Mcl-1 protein expression via the ubiquitination pathway." (PMID 34576269, 2021). "The levels of ABCG2, C-Myc, Bmi1, and Sox2 were repressed by the depletion of circNOLC1 in MDA-MB-231 and MDA-MB-468 cells, implying that the inhibition of circNOLC1 attenuates cancer stem cell properties." (PMID 34789263, 2021). "Not surprisingly, silencing of BMI1 has been suggested as a promising therapeutic target in many human cancer therapies." (PMID 33407350, 2021). "During cancer progression, stemness of cancer cells is maintained by hypoxia through different mechanisms, including enhancement of EMT and the transcriptional induction of stemness related genes (Oct4, POU5F1, Sox2, Nanog, BMI1, Myc and KLF4)." (PMID 33407613, 2021). "Besides, co-exposure to sodium butyrate and ATRA decreased the expression of cancer markers MYCC (3-fold) and Bmi1 (2-fold) while also downregulating the differentiation markers β-3 tubulin (2-fold) and NeuN (2-fold) in SH-SY5Y and SK-N-BE cell lines." (PMID 33809565, 2021). "To determine whether the change in cancer stem cell fraction occurs due to a numerator or a denominator effect, we used immunocytochemistry to evaluate ALDH1 and Bmi-1 expression on a single-cell basis." (PMID 34689150, 2021). "The expression of other PcG subunits, such as BMI1, is also enriched in GBM cancer stem cells, although in a different GSC population, indicating that dual targeting of multiple PRC complexes may be necessary." (PMID 34617019, 2021). "We also detected significantly high expression of OCT4, SOX2, KLF4 and BMI1 in the HPV-negative OPC CSCs as compared to the cancer cells, while CD133 expression was not different in the CSCs and the cancer cells." (PMID 34359786, 2021). "“MYC”, “BMI1”, “MEL18”, and “KRAS” collections played oncogenic roles in cancer course." (PMID 34094897, 2021). "This study demonstrates that inhibition of BMI-1 decreases the cancer stem-like cell population and induces apoptotic cell death in cancer cells, but not in normal cells." (PMID 34576269, 2021). "Pharmacological BMI1 inhibitors such as PTC-209 and PTC-296 have shown promising results in different types of cancers, but associated treatments have not yet been offered." (PMID 33918475, 2021). "Therefore, our results suggest that the inhibition of BMI-1 induces DUB3-dependent Mcl-1 degradation, resulting in the enhancement of cancer apoptosis." (PMID 34576269, 2021). "The expression of stem cell markers such as ALDH1, BMI-1, CD44, Nanog, and SOX2 is well-investigated for other tumour entities, and has shown promising results as prognostic parameters with potential as a target for cancer treatment." (PMID 33009929, 2021). "Since our results indicate that low concentrations of PTC596 (10 nM) increased cancer cell apoptosis through BMI-1-dependent Mcl-1 downregulation, we ruled out the effect of PTC596 as a novel small-molecule tubulin binding agent." (PMID 34576269, 2021). "Compared with control xenograft tumors, the mRNA levels of cancer stemness-related genes, including ABCG2, BMI1, NANOG, KLF4, and OCT4 were increased and the protein expression of ABCG2, Oct4, Bmi-1, and CD44 were also increased in HBx-expressing xenograft tumors." (PMID 32168902, 2020). "Bmi1, a member of the polycomb-repressive complex 1 (PRC1), participates in the self-renewal of hematopoietic and neural stem cells, embryogenesis, cell cycle regulation, senescence, chemoresistance, recurrence of cancer stem cells, and tumor progression." (PMID 33014838, 2020).
cancer (continued). "CSCs Self-renewal may be retained through multiple endogenous signaling paths, including Wnt, Bmp, Pten, Notch, B cell–specific Moloney murine leukemia virus integration site 1 (Bmi1), TGF-β, and Hedgehog that would be often actuated in human cancers." (PMID 32280305, 2020). "SOX2, BMI-1, and PROM1 are cancer stem cells-related genes, and TWISTNB is implicated in EMT." (PMID 32118031, 2020). "In line with this, it has been demonstrated that nicotine plays a critical role in the development of tobacco-induced cancers by increasing the expression of various CSC markers NANOG, OCT4, CD44, and BMI-1 and regulating CSC properties and tumorigenic potential in HNSCC models in vitro and in vivo." (PMID 32635524, 2020). "More importantly, we also found that circ_001680 could promote the cancer stem cell (CSC) population in CRC and induce irinotecan therapeutic resistance by regulating the miR-340 target gene BMI1." (PMID 32005118, 2020). "In addition, we found that BMI1 induced the EMT process and enhanced cancer stemness when overexpressed in A549 cells." (PMID 32726929, 2020). "In addition to CSC markers, targeting cancer stemness genes has been found to have potential for EC treatment, such as B-lymphoma Mo-MLV insertion region 1 (BMI1) or homeobox transcription factor Nanog (NANOG)." (PMID 33334065, 2020). "Altogether, we were able to show mitotic arrest and cytotoxicity caused by BMI1 loss in two commonly used NSCLC in vitro models, indicating that the observed phenotypes related to BMI1 inhibition extend to non-haploid cancer cells as well." (PMID 32343689, 2020). "Interestingly, our data show for the first time that PTC-209, a selective inhibitor of BMI-1, inhibits gp130-STAT3 pathway in cancer cells." (PMID 31695609, 2019). "In HCT-15 cells, reduced transcription of cell cycle mediating genes (CCND1, PCNA, CDK2, CDKN1B), and reduced transcription of anti-apoptotic genes (BMI1, BIRC5 and BCL2), support a cancer suppressive and favorable FOXO3/FOXM1 ratio upon combined TNKSi/MEKi treatment." (PMID 30717152, 2019). "In this study, ChIP-seq was performed on an LCL for BMI1 and SUZ12, subunits of PRC1 and PRC2, respectively—two protein complexes shown to be critically important in the regulation of genes involved in differentiation, proliferation and cancer development." (PMID 30649516, 2019). "miR-34a inhibits cancer stemness via targeting CD44; miR-34a expression inhibits TGF-β-induced EMT and downregulates Snail, Slug and ZEB1 as well as the stemness factors (BMI1, CD44, CD133, OLFM4 and c-MYC)." (PMID 30885232, 2019). "Indeed, PTC-209 was able to downregulate the level of Bmi-1 transcript in the human colorectal HCT116 and fibrosarcoma HT1080 cancer cells." (PMID 31695609, 2019). "Furthermore, knockdown of PKM2 combined with IR markedly reduced the expression of several cancer stem cell biomarkers in vitro, including NANOG, OCT4, SOX2, and Bmi1." (PMID 31114449, 2019). "Furthermore, recent evidence suggests that co-downregulation of multiple such epigenetic pathways, including BMI1 and EZH2, is needed to obtain a significant biological effect in cancer cells." (PMID 30683859, 2019). "Here, we demonstrate that, unlike the canonical transcriptional repressor and its functions in cancer stem cells, BMI1 performs its noncanonical function as a transcriptional activator and an AR cofactor." (PMID 29402932, 2018). "In this study, we analysed eleven death-from-cancer signatures in survival of cancer patients and demonstrated that USP22 plays vital roles in gastric CSC self-renewal and GC progression by stabilizing BMI1 and regulating the expression of stemness genes such as CD133, SOX2, OCT4 and NANOG." (PMID 28415621, 2017). "Interestingly, the phosphorylated species of BMI1 was present in all the cancer cell lines including OV90 that expressed minimal phospho-AKT, thereby implicating other kinases in phosphorylation of BMI1." (PMID 28270146, 2017).
cancer (continued). "Our observations indicate that not all of Bmi1+ or Lgr5+ tumorigenic cells behave as cancer stem cells." (PMID 28176811, 2017). "Treatment with PTC-209 was shown to be specific to BMI-1, downregulating the protein levels in cancer cells and had no to limited effect on cell growth and viability in normal cells, indicating that PTC-209 activity is not due to cytotoxicity." (PMID 28968963, 2017). "Moreover, we also found that Bmi1-mediated migration and invasion of TSCC involves cancer stem-like cells and the SOD2-H2O2 pathway." (PMID 27926482, 2017). "We showed that knockdown of miR-218 in ALDH1−CD44− non-OCSCs enhanced cancer stemness, while silencing of Bmi1 significantly counteracted it." (PMID 27926533, 2017). "Importantly, our study reveals a regulatory pathway consisting of BMI1, let‐7i, and ERK3 that is important for controlling cancer cell migration." (PMID 28079973, 2017). "Notably, Bmi1 overexpression induces chemotherapy and radiation resistance in various cancers and platinum resistance in OVCA compatible with a role for Bmi1 to drive treatment‐resistant ovarian CSC." (PMID 28179359, 2017). "In addition, the levels of cancer stem cell markers, such as aldehyde dehydrogenase-1, cluster of differentiation 133 (CD133), CD44, Lgr5, Musashi-1, Ephrin receptor, and Bmi-1 increased after exposure to BP compounds." (PMID 28862656, 2017). "This was probably because the method randomly induces multiple cancers and is therefore not appropriate for investigations of specific cells, such as Bmi1+ tongue stem cells, in tumor generation." (PMID 28004815, 2016). "YY1 shares many properties with cancer stem cells (CSCs) that drive tumorigenesis, metastasis and drug resistance and are regulated by overexpression of certain transcription factors, including SOX2, OCT4 (POU5F1), BMI1 and NANOG." (PMID 27225481, 2016). "To further characterize Bmi1 and Ring1b expression as well as H2AK119ub levels in ADM formation and tumor development, we set up an in vitro cell culture system, mimicking the steps of cancer progression from normal acinar cells to ADM and PDAC." (PMID 26716510, 2016). "Recently, Pier Paolo Pandolfi and colleagues found miR-22 promotes the EMT, tumor invasion and metastasis of normal and cancer mammary stem cells by targeting TET1, TET2 and TET3; miR-22 overexpression enhances some stemness and EMT-related genes expression, such as BMI1, ZEB1 and ZEB2." (PMID 26349457, 2016). "Markers generally considered to be expressed on cancer stem cells (DLG7, BMI1, CD44s, CD26) showed a strong trend towards upregulation in CTCs, 2 out of the 4 genes reached statistical significance (DLG7, p = 0.009; BMI1, p = 0.03)." (PMID 27029058, 2016). "Hes1 binds to the Bmi-1 locus and upregulates Bmi-1expression, which consequently downregulates PTEN and activates the Akt/GSK3β pathway, induces EMT and cytoskeleton reconstruction, ultimately leads to enhanced invasiveness of cancer cells." (PMID 26452029, 2015). "Bmi1, the polycomb group protein B lymphoma Mo-MLV insertion region 1 homolog, regulates EMT transition, maintains the self-renewal capacity of stem cells, and is frequently overexpressed in human cancers." (PMID 26023734, 2015). "We found that the mRNA expression of BMI1 was significantly higher in the cancer specimens compared with their paired non-tumor specimens (n=33; P<0.01)." (PMID 25999024, 2015). "For example, expression of BMI1 polycomb ring finger oncogene (BMI1), a component of PRC1 and an important factor in stem cells, was found to be correlated to patient outcome in several types of cancer." (PMID 25243792, 2014). "Our results suggest that miR-302a acts as a tumor suppressor and suppresses the cancer-stemness signature in cancer cells by suppressing target genes such as CDK2 and BMI-1, although it has an important role in maintaining stemness in pluripotent cells such as ES cells and iPS cells." (PMID 24861464, 2014).
cancer (continued). "Interestingly, upregulation of USP22 accompanies with the regulation of the BMI-1 pathway and c-Myc pathway in ACC-83 cancer cell lines." (PMID 24466336, 2014). "Moreover, USP22 acts as an oncogene by regulation the BMI-1 pathway and c-Myc pathway in ACC-83 cancer cell lines." (PMID 24466336, 2014). "Cancer stem cells have been shown to produce cytokines, chemokines, angiogenic factors, and possess up-regulated signaling cascades essential for cancer metastasis, including hedgehog, epidermal growth factor receptor, NOTCH, and Bmi-1." (PMID 22592563, 2013). "The polycomb gene BMI1, a component of PRC1, is overexpressed in several human cancers so that it might be expected that aberrations in this system would give rise to global alterations in gene silencing in cancer." (PMID 23086271, 2013). "The relationship between TAMs and Bmi1 expression was analyzed by immunohistochemistry and quantitative real-time PCR (qRT-PCR), and results showed a positive correlation with tumor-infiltrating macrophages (CD68 and CD163) and Bmi1 expression in cancer cells." (PMID 24312366, 2013). "Bmi-1 is essential in EMT process, and EMT also mediates radioresistance in human cancer cells." (PMID 22209830, 2012). "Together with Polyhomeotic 1 and Chromobox protein homologue 4, Ring1B and Bmi1 form the core human Polycomb transcriptional Repressive Complex 1 (PRC1), which plays a critical regulatory role in the control of genes during development, ageing and cancer." (PMID 22194680, 2011). "Overexpression of Bmi-1, ABCG2 and cyclin D1 and downregulation of p16 could contribute to these phenotypic changes of Panc-1 cancer stem cells." (PMID 21673909, 2011). "Bmi-1 expression was significantly increased in primary cancer tissues compared with matched adjacent non-cancerous tissues (χ2 = 20.237, ***P < 0.001)." (PMID 21276221, 2011). "In this study, differential expression of Bmi-1 was detected between primary cancer tissues and the matched adjacent non-cancerous tissues." (PMID 21276221, 2011). "Furthermore, Expression of BMI-1, GLI1, GLI2, GLI3 and a list of cancer related microRNAs were also quantified." (PMID 21826251, 2011). "Bmi-1 expression is more pronouncedly increased in primary cancer tissues compared to matched adjacent non-cancerous tissues." (PMID 21276221, 2011). "Here, we presented Bmi-1 was upregulated in ESCC and the expression of Bmi-1 in ESCC was mainly in nuclei of tumor cells, which was in accordance with the findings in the studies of other cancers." (PMID 20809956, 2010). "In the remaining 88 informative cancers without amplification of Bmi-1, 60 (68%) cases showed low expression of Bmi-1, while 28 (32%) cases were observed intensive expression of Bmi-1." (PMID 20377880, 2010). "The expression level of Bmi-1 protein in cancer tissue was higher than that in the paired non-tumor tissues." (PMID 20809956, 2010). "Despite its established role in stem cell maintenance, cancer and development, at present not much is known about the functional domains of BMI1 oncoprotein." (PMID 20569464, 2010). "We found that Bmi-1 expression was higher in the immortalized cells, cancer cell lines and most cancer tissue than in non-tumorous control tissue at both mRNA and protein level." (PMID 20809956, 2010). "Bmi-1 protein expression is up-regulated to a greater extent than is Bmi-1 mRNA expression in cancer tissues relative to non-cancerous tissues." (PMID 19228380, 2009). "Nuclear co-localization of CTIP2 protein and cancer stem cell (CSC) marker BMI1 was observed in most, if not all of the cells expressing BMI1 in moderately and poorly differentiated tumors." (PMID 19399189, 2009). "It was observed that PTEN co-localizes with BMI1 more extensively in PINs compared to both carcinomas and normal prostate glands." (PMID 19903340, 2009). "Although all studies analyzing the deregulated expression of Bmi-1 have been conducted in primary tumors, no data on Bmi-1 in plasma of cancer patients have been reported." (PMID 17711569, 2007).
cancer (continued). "The BMI1 gene (the protein product of which is a part of the PRC1 complex) was also hypomethylated in many regions not only in hgOvCa (exons, 3′UTR and distal promoter) but in both carcinoma groups (proximal promoter and the first exon), which implies its high expression in OvCa (GR file)." (PMID 39456618, 2024). "In other cancers, Bmi-1 has been a more promising negative prognosticator." (PMID 36726797, 2023). "However, due to their associated toxicity and side effects, HDAC inhibitor-mediated reduction of BMI1 expression is unlikely to be useful for cancer therapy." (PMID 33804165, 2021). "We examined the effects of cigarette smoke condensate (CSC) on the formation of cancer stem-like cells, which are rich in octamer-binding transcription factor (OCT)-4, inhibitor of differentiation 1 (ID1), nuclear factor (NF)-κB, and B lymphoma Mo-MLV insertion region 1 homolog (BMI-1)." (PMID 33442406, 2021). "Moreover, the addition of kynurenine to tumorsphere cultivation significantly increased the tumorsphere number of HeLa and SiHa cells, as well as the increased expression of Oct4 or Sox2 but not BMI1, which all belong to the well-known cancer stemness genes." (PMID 32545442, 2020). "Taken together, the mRNA and the protein levels of Bmi1 were not strictly correlated in NPC cancer cells and tissues, indicating that Bmi1 expression was not only regulated in the transcriptional level but may also be regulated in the post-transcriptional level in NPC cells and cancer specimens." (PMID 33014838, 2020). "Notably, despite the key role of Bmi1 in the self-renewal of various somatic cancer stem cells that has been reported, there is no research focusing on Bmi1 in ESCC." (PMID 32884573, 2020). "Furthermore, the BEP seems to inhibit cancer stemness property since the treatment of MDA-MB-231 cells with BEP mitigated colony formation while it simultaneously inhibited stemness-related (CD44 and BMI-1) gene expressions." (PMID 30691094, 2019). "There are currently no drugs that specifically target cancer stem cell fractions, and a reduction in BMI-1 protein induced by PTC596 may offer a novel therapeutic strategy for MCL." (PMID 29983879, 2018). "Thus, whereas ongoing repression of miR-200 in the cancer cells was sufficient for continued expression of Bmi1, it was not sufficient to maintain CD44hi." (PMID 29930325, 2018). "There are currently no drugs that specifically target cancer stem cell fractions, and a reduction in BMI-1 protein by PTC596 may offer a novel therapeutic strategy for MCL." (PMID 29983879, 2018). "On the other hand, single fluorescent cells that expressed Bmi1 at the time of tamoxifen injection but did not divide thereafter were observed both at days 7 and 28 after induction in all three models, indicating that not all Bmi1+ cells in tumors behaved as cancer stem cells." (PMID 28176811, 2017). "Based on the results of this study, we propose a novel molecular mechanism for the upregulation of ERK3 in cancer: BMI1 suppresses the transcription of the miRNA let‐7i, a negative regulator of ERK3 expression, which leads to elevation in ERK3 protein level and increase in cancer cell migration." (PMID 28079973, 2017). "Our results showed that EGF induces EMT process in OSCC cells, which correlates with the acquisition of cancer stem-like properties, including the enrichment of CD44+/CD24− population of cancer cells and an increased expression of CSC-related genes, aldehyde dehydrogenase-1 (ALDH1) and Bmi-1." (PMID 27926487, 2017). "In addition, FOXC2, SALL4, CSF1 and BMI1 mRNA levels were also increased in Hep3B-TFF3 cells, all of which have recently been suggested to be involved in promoting CSC-like characteristics in various cancer cells." (PMID 28445151, 2017).